CCND1 (cyclin D1)
Diseases named in the same sentence as CCND1 in open-access papers (continued):
Sharing a sentence is not in itself a finding about the gene and the disease.
cancer (continued). "Cyclin-D1 plays the key role in regulation of the cell cycle progression of cancer cells and in HTB-35 cells exposed to Met the two-fold decrease of CCND1 transcript level was found under normoxia (p < 0.05 vs. untreated control) and under hypoxia as well (p < 0.05 vs. untreated control)." (PMID 29958416, 2018). "Furthermore, using cancer patients’ cell-free DNA, we develop PCR-based EBV copy and CNV tests (CCND1 and CDKN2A) to provide drug guidance information." (PMID 30236142, 2018). "Cyclin D1 is not expressed in normal colorectal tissue, but its overexpression has been confirmed in many cancers, including colorectal carcinoma." (PMID 30551667, 2018). "The k-core factor was then applied to identify key regulatory genes, which likely play pivotal roles in gene interactions and regulation, including for key cancer genes, such as p21, FAS, CCND1, and CDK2; real-time PCR confirmed these genes after knockdown of HOXC-AS3." (PMID 30286788, 2018). "CCND1 is a proto-oncogene that regulates progression through the G1-S phase of the cell cycle; moreover, it has been observed to be switching to proximal APA sites in cancer cells." (PMID 29717174, 2018). "Cancer cells often over-express cell cycle proteins such as cyclin D1 and drive the cycle to proliferation without any interruption." (PMID 29755565, 2018). "Moreover, the findings from the gene expression confirmed the over expression of Bax, and under expression of cyclin D1 following treatment with dichloromethane (DCM) and n-hexane (n- hex) extracts in cancer cells (P < 0.05)." (PMID 30607339, 2018). "Tissue culture experiments demonstrated that the effect of SHetA2 on cyclin D1 in non-cancerous cells was much reduced in comparison to cancer cell lines." (PMID 29273857, 2018). "Alterations in cyclin D1 turnover in cancer can lead to nuclear accumulation of cyclin D1 independent of changes in cyclin D1 mRNA expression." (PMID 29330435, 2018). "Interestingly, the expression level of cyclin D1 mRNA decreased after treatment with DCM and n-hex extracts in the treated cancer cells compared to untreated control cells (p<0.05)." (PMID 30607339, 2018). "CCND1 IHC staining after drug treatment revealed homogenous overexpression in the PAL-treated group, implying that the drug arrests the cell cycle of cancer cells at G1/S phase." (PMID 30236142, 2018). "Cytoplasmic expression of cyclin D1 can control cancer cell migration, invasion, and metastasis, but not cell proliferation." (PMID 30428594, 2018). "CCND1 (FC 2.59), BCL2L1 (FC 2.25), MYC (FC 3.70), along with CCND2 (FC 1.60) and SOCS7 (FC 1.51), are all located downstream of STAT activation and were upregulated in carcinoma tissue." (PMID 30603058, 2018). "More importantly, concomitant treatment with statins and the NF-κB inhibitor (CAPE) synergistically induced anti-cancer activities including the attenuation of proliferation and growth along with downregulation of LIN28B and cyclin D1, and restoration of let7-miRNA expression in human CRPC cells." (PMID 28910332, 2017). "We were interested to examine the mechanism of anti-cancer drug-resistance conferred by CAGE.We present evidence that CAGE confers anti-cancer drug-resistance by binding to GSK3β and increasing the expression of cyclin D1 and pGSK3βSer9." (PMID 28099142, 2017).
cancer (continued). "According to subgroup analysis by cancer type, the risk of sporadic colorectal cancer (sCRC) and hereditary nonpolyposis colorectal cancer (HNPCC) were not correlated with the CCND1 G870A polymorphism, except AG (AG vs GG: OR = 1.30, 95% CI = 1.11–1.53)." (PMID 29049220, 2017). "The results of the present research indicated that considering changes in the expression of cyclin D1 and E-cadherin markers in groups treated with HESA-A, HESA-A has preventive effects on the development of cancer in dysplastic lesions through regulation of expression of these molecules." (PMID 29354245, 2017). "Although cyclin D1 overexpression has been regraded to be a common event in the variety of cancer, cyclin D1 overexpression does not occur solely as a consequence of gene amplification." (PMID 28870200, 2017). "Our data confirm that non-canonical, CDK-dependent and -independent cyclin D1 functions are common to many cancer cells." (PMID 29066743, 2017). "Cyclin D1-mediated increases in stemness-CSC properties may contribute to therapy failure and cancer recurrence." (PMID 28415588, 2017). "Moreover, the gene microarray indicated knockdown of PSMC2 notably changed a number of genes, especially some cancer related genes including ITGA6, FN1, CCND1, CCNE2 and TGFβR2, and whose expression changes were further confirmed by western blotting." (PMID 27888613, 2017). "Data indicate that this may be mediated, at least in some of these cancers, by deregulation of multiple alternative mitogenic pathways (for example, HER2, PI3K/AKT, and so on) that can potentiate cyclin D1:CDK4/6 signaling in an ER-independent fashion." (PMID 26857361, 2016). "The effect of JQ1 on MSCs in our study, as well as on cancer cell lines in the other studies, are in line with the previous studies showing that BRD4 activates the transcription of CCND1 and CCND2, and that their expression is reduced in NIH3T3 cells after knockdown of BRD4." (PMID 26830473, 2016). "A particular study indicates that ZnPP suppresses cyclin D1 gene expression in cancer cells is HO-1 independent, but SnPP does not." (PMID 26822586, 2016). "By immunohistochemistry, Ccnd1 shows a diverse pattern of localizations in cancer tissues and cytoplasmic accumulation does not mean nuclear exclusion and vice versa (; our results)." (PMID 27105504, 2016). "Recent studies also show that Cyclin D1 overexpression in cancers does not occur solely as a consequence of gene transcription and amplification, also results from regulation at the post-translational level in several cancers." (PMID 27095572, 2016). "TFF2 suppresses IMC/MDSC proliferation in part through downregulation of cyclin D1 (and possibly through upregulation of cell-bound ApoE) thus reducing MDSCs and liberating anti-tumorigenic CD8+ T cells to inhibit the development of cancer." (PMID 26841680, 2016). "Of the 264 primary cancer specimens, 51.9 % (137/264) showed positive cyclin D1 expression, whereas only 12.5 % (33/264) of the adjacent normal mucosae were positive." (PMID 26791264, 2016). "This study supports the hypothesis that PF exerts anti-cancer activity, and downregulation of cyclin D1 and CDK4 plays a role in PF-induced anti-cancer activity." (PMID 27670681, 2016). "More specifically, CD24 could act from the cell membrane through BMI1 and/or Nanog to control the expression levels of MDR genes, CCND1 and DNA repair genes like L1CAM and NBS1 to combat cisplatin-induced toxicity and damage to the cancer cells." (PMID 27276062, 2016). "Importantly, HDN-1 degrades multiple client proteins, such as EGFR, Stat3, Akt, Erk, Raf, Cyclin D1, and HIF, all of which have been reported to be oncoproteins to promote cancer development." (PMID 25742791, 2015).
cancer (continued). "The expression of Cyclin D1, FOXP1, FIH-1, pan-ERβ, NRP1 and CD99, predicted to be regulated by BRCA1 specific miRNAs by computer prediction algorithms, was assessed via immunohistochemistry in a cohort of 35 BRCA1 and 52 sporadic basal-like cancers." (PMID 26152113, 2015). "BRCA1 basal cancers, when compared to sporadic basal cancers showed reduced positivity for FOXP1 (6/20 [30 %] vs. 37/49 [76 %], p < 0.001), cyclin D1 (8/22 [36 %] vs. 30/46 [65 %], p = 0.025), NRP1 (2/20 [10 %] vs. 23/46 [50 %], p = 0.002) and CD99 (17/20 [85 %] vs. 7/19 [37 %], p = 0.002)." (PMID 26152113, 2015). "Based on the functional characteristics and cancer-specific expression pattern of PPP2R2A (B55α) and Cyclin D1, it is evident that both PPP2R2A and the PPP2R2A-/low/Cyclin D1high phenotype deserve further attention to better uncover their possible clinical and biological importance in BC." (PMID 25879784, 2015). "NF-κB pathway plays an important role in regulating cancer cells proliferation, anti-apoptosis, invasion and metastasis and angiogenesis, through modulating series of functional genes expression and activity, including IL1A, CCND1, MYC, Bcl-2, MMP9 and VEGF." (PMID 26429874, 2015). "CCND1 and CCND2 are well-established oncogenes in many different cancers." (PMID 26325180, 2015). "Of the six proteins that were investigated via immunohistochemistry, four (cyclin D1, FOXP1, NRP1 and CD99) showed reduced expression in BRCA1 cancers in the initial cohort with reduced expression for FOXP1, cyclin D1 and NRP1 subsequently confirmed in the validation cohort." (PMID 26152113, 2015). "Of note, the CCND1 and CDKN2A loci show some of the highest frequencies of amplification and deletion rates seen in SCCHN and several other cancer types; this further supports the idea that it may be important to restrain RB1 function post-translationally." (PMID 26265441, 2015). "While in theory these inhibitory compounds should be effective in cancer cells that are dependent on either one of the cyclin Ds (cyclin D1, D2 or D3), it is not clear if in practice they show such a general effect." (PMID 25645078, 2015). "Compared with sporadic basal cancers, BRCA1 cancers showed reduced positivity for proteins predicted to be regulated by miRNAs: FOXP1 (6/20[30 %] vs. 37/49[76 %], p < 0.001), cyclin D1 (8/22[36 %] vs. 30/46[65 %], p = 0.025), NRP1 (2/20[10 %] vs. 23/46[50 %], p = 0.002)." (PMID 26152113, 2015). "In addition to CCND1, there are several other suggested targets for miR-193b, such as YWHAZ,PLAU(aka uPA), and KITin different cancer types 9–16." (PMID 26129688, 2015). "Moreover, increasing evidence supports a role for cyclin D1 and CDK4 in the promotion of cancer cell proliferation, and they are more abundant in lung tumor tissue than normal lung tissue." (PMID 25971210, 2015). "Similarly to our results, other studies in cancer samples revealed a correlation between nuclear EGFR localization and Cyclin D1 expression." (PMID 25991665, 2015). "The significant down-regulation of cyclin B, cyclin D1, E2F1, survivin, and c-MYC in human RCC cells mediated by ART may be sufficient to arrest cell cycle progression and to suppress cancer stemness." (PMID 26426994, 2015). "In agreement with the advanced carcinoma observed in animals fed with HFD and consistent with a previous report, expression of cyclin D1 was elevated and immunohistochemistry revealed high intensity of cyclin D1-positive clusters within these tumors." (PMID 26053034, 2015). "However, miR-497 can also attenuate the malignancy of cancers by regulating other targets, such as TARBP2, DICER, BCL2, CCND1, CCNE1, CDC25A, CCND3, CDK4." (PMID 24667580, 2014). "We also demonstrated that lentivirus-based knockdown of KLF5 inhibited cancer cell growth, while over-expression of a Flag-tagged KLF5 could partially reverse the effects of curcumin on cell growth and cyclin D1 expression." (PMID 25170806, 2014).
cancer (continued). "To explain the biological mechanism of cell proliferation suppression by doxazosin concerning cell cycle changes, we observed both, an inhibition of cell cycle-regulatory proteins such as cyclin D1 and CDK4, and expression of p21 in doxazosin-treated carcinoma cells." (PMID 25568671, 2014). "In contrast to the hypophosphorylation of pRB, decrease in cyclin B1 and increase in cyclin D1 in ASH-WEX and TEG-treated cancer cells (undergoing growth arrest), normal cells showed increase in pRB phosphorylation and cyclin B1, and decrease in cyclin D1 (signifying their cell cycle progression)." (PMID 24130852, 2013). "Although the roles for BIRC5 and OCT4 in cancers are well-recognized in a number of previous studies, we gave the first evidence that OCT4 indirectly manipulates the expression and function of BIRC5, and also directly upregulates the expression of CCND1." (PMID 23433354, 2013). "Immunostaining intensities of cyclin D1 in the cancer cells of the RCC patient specimens did not correlate significantly among the three genotype groups of rs7105934 (P=0.844) or the GG and GA + AA genotypes of rs7105934 (P=0.884)." (PMID 24137339, 2013). "The prognostic significance of cyclin D1 overexpression with respect to cancer in general does not seem to be consistent, however." (PMID 23336272, 2013). "Also, cyclin D1 is overexpressed in many cancers, and sustained ERK activation leads to the induction of cyclin D1." (PMID 24223164, 2013). "Overexpression of ATF3 increased CCND1/2 expression in PC3 and DU145 cancer cells." (PMID 23591848, 2013). "Cyclin D1 has several regulatory effects in normal cellular differentiation, growth and metabolism; however, the overexpression of CCND1 is one of the most commonly observed alteration in human cancers, as it has cell-cycle regulatory effects in G1 phase." (PMID 24098334, 2013). "It has, however, been reported that the oncogenic activity of cyclin D1 in human cancers is independent of CDKs." (PMID 23336272, 2013). "In addition, the levels of phosphorylated retinoblastoma (pRB, a downstream effector of cyclin D1) and matrix metalloproteinase 9 (MMP-9, a downstream gene of Ets1) were decreased in miR-9 over-expressing cancer cells." (PMID 23383271, 2013). "We have previously reported that inhibition of EGFR signalling axis and activation of PPARγ axis are both effective in significantly inhibiting proliferation of human carcinoma cells through different pathways, in part converging to PI3K/Akt, cyclin D1, and cyclin-dependent kinase inhibitors." (PMID 23409107, 2013). "A recent study of human cancer cell lines showed that ZSTK474 has potent effects on arrest of cell cycle progression through inhibition of phosphorylation or expression of Akt and/or mTORC1 substrates, such as p-GSK3β, p-mTOR, p-p70S6K and cyclin D1." (PMID 22647622, 2012). "Finally, we investigated the roles of cyclin D1 and MMP7 in gland and cancer formation in the mouse, and assessed the relevance of Lef1 to human cancer by comparing expression levels in cancerous and normal endometrial tissues." (PMID 22792274, 2012). "The two experimentally proved targets involved in invasion-inhibiting effect of miR-195 in cancer cells, CCND1 and CCND3, are not influenced by miR-195 in human trophoblastic HTR8/SVneo cells." (PMID 22723898, 2012). "As a repressor of cancer cell growth, DKK1 is a main antagonist that interferes with the WNT pathway and downregulates the expression of the downstream target genes including Cyclin D1." (PMID 22815877, 2012). "Adding ERα over-expression to cyclin D1 over-expression increased the prevalence of hyperplasia but not cancer." (PMID 24575359, 2012). "Single dose DMBA exposure did not increase cancer prevalence in any of the genotypes although cyclin D1 over-expressing mice demonstrated a significant increase in hyperplasia." (PMID 24575359, 2012).
cancer (continued). "In addition, six of the frequently hypermethylated genes, i.e., CCND1, COL4A2, HDAC2, AXIN2, ABL1 and GLI2, are included in the pathways in cancer map from the KEGG database." (PMID 22159500, 2012). "Most slides from cancer-free tissue lacked expression of CCND1, CD44, CDH1, EGFR, ERBB2, KIT, keratins, NOTCH1, PAK1, PTGS2, SNAI1, and VIM but showed staining of MUC1, HIF1A, NKX2-1, SFTPC, and STAT3, which were also found in AdCa." (PMID 23028920, 2012). "Cyclin D1 is over-expressed in a variety of human cancers that do not exhibit cyclin D1 gene amplification or structural abnormalities of the cyclin D1 locus, which suggests that increased Cyclin D1 stability is a potential mechanism." (PMID 21347341, 2011). "Increased expression of Cyclin D1 has been seen in a number of cancers; however, this enhanced expression is usually not sufficient to drive the oncogenic process." (PMID 21347341, 2011). "In particular, the median levels of autoantibodies to Cyclin A, Cyclin D1, and survivin are lower in the group with ground glass opacities compared with the groups with cancer, no nodules, or solid nodules." (PMID 20504322, 2010). "Future investigations may wish to focus on the transcriptional influence of CRY2 on oncogenic CCND1, and the relationship with CDKN1A, as these findings have the potential for broad impact on a number of cancer types." (PMID 20334671, 2010). "Not all of the cancer cell lines expressed the same STAT3 downstream targets but cyclin D1, Bcl-2, survivin, DNMT1 and TWIST1 were among the most common STAT3 downstream targets expressed and were inhibited by the STAT3 inhibitor, FLLL32." (PMID 20712901, 2010). "In addition to IL-6, the expression of cyclin D1, c-myc, survivin, Bcl2, Mcl1, and VEGF, all of which are regulated by Stat3 activity, and play a crucial role in apoptosis and progression of cancer, are also down regulated in response to avicin D." (PMID 19440292, 2009). "High cyclin E expression correlated with triple negative cancers (p = 0.0474), while cyclin D1 expression correlated with non-triple negative carcinomas (p = 0.0156) and non-basal-like carcinomas (p = 0.0279)." (PMID 19615042, 2009). "Nevertheless, we observed a significant positive correlation between immunoreactivity of cyclin D1 and hormone receptors as well as with non-basal-like carcinomas and non-triple negative carcinomas." (PMID 19615042, 2009). "In contrast, lost regions at 3p and 5q as well as amplifications at 11q13.3 (CCND1 locus) were frequent in hrHPV-negative carcinomas, but not in hrHPV-positive carcinomas." (PMID 19486517, 2009). "Gene by gene functional analyses have revealed that cyclin D1, FADD and cortactin are potentially able to enhance cancer development." (PMID 18268491, 2008). "With respect to S-phase events both mouse models and studies on cancer-derived cells revealed that accumulation of cyclin D1/CDK4 complexes triggers DNA re-replication and, thus, could be specifically targeted in cancer cells." (PMID 18509533, 2008). "Cyclin D1 overexpression is a common event in cancer but does not occur solely as a consequence of gene amplification." (PMID 17407548, 2007). "Cyclin D1-positive phenotype was increased in primary carcinoma compared to non-neoplastic tissue, and was evident in all lymph node metastases cases." (PMID 17375037, 2007). "Our results show however, that the inhibition of GSK3β or CRM1-dependent nuclear export does not result in the effective nuclear accumulation of cyclin D1 in mammalian cancer cell lines." (PMID 16503970, 2006). "We mimicked 11q13 amplification by generating MMTV-cortactin/-MMTV-cyclin D1 bitransgenic mice but did not observe any synergistic effect of cortactin on cyclin D1-induced mammary hyperplasias or carcinomas, nor development of distant metastasis." (PMID 16536875, 2006).